KHSRP (KH-type splicing regulatory protein)
Diseases named in the same sentence as KHSRP in open-access papers (continued):
Sharing a sentence is not in itself a finding about the gene and the disease.
infection (7 papers, 2012 to 2025). The state of being infected such as from the introduction of a foreign agent such as serum, vaccine, antigenic substance or organism. "KHSRP regulates a variety of critical cellular processes, including metabolism, differentiation, proliferation, and infection response." (PMID 40572705, 2025). "However, two immune-regulatory genes (IRF7 and KHSRP) were not responsive to highly pathogenic H5N1 infection but were strongly up-regulated in DF-1 cells infected with low pathogenic H9N2 infection." (PMID 25557928, 2015).
KHSRP also shares sentences with these, for which no sentence is quoted: Arthritis (3 papers); hepatocellular carcinoma (3); sarcoma (3); Sepsis (3); type 2 diabetes (3); asthma (2); atherosclerosis (2); autoimmune disease (2); cervical carcinoma (2); inflammation (2); lupus (2); lymphoma (2); ovarian carcinoma (2); rheumatoid arthritis (2); acute liver failure (1); allergic asthma (1); Allergy (1); Autoimmunity (1); clear cell renal cell carcinoma (1); colon cancer (1); conjunctival melanoma (1); COVID-19 (1); cryptosporidiosis (1); diabetes (1); fungal infection (1); glomerulonephritis (1); hematologic malignancies (1); Insulin resistance (1); kidney inflammation (1); leukemia (1).
A further 10 diseases each share a sentence with KHSRP in 1 paper.